PIGF (phosphatidylinositol glycan anchor biosynthesis class F)
Diseases named in the same sentence as PIGF in open-access papers (continued):
Sharing a sentence is not in itself a finding about the gene and the disease.
Hypertension (9 papers, 2017 to 2025). The presence of chronic increased pressure in the systemic arterial system. "Regarding biomarkers for screening, there is a lack of consensus among clinicians and researchers: in 2018, the International Society for the Study of Hypertension in Pregnancy recommended against the use of PIGF." (PMID 38731197, 2024). "In fact higher levels of circulating anti-angiogenic factor sFlt1 and lower levels of circulating angiogenic factor, PIGF was found among women with previous Hypertensive Disorders of Pregnancy who had unresolved hypertension post-partum." (PMID 31841512, 2019). "The sFlt-1/PlGF ratio was positively correlated with ABPM BP parameters, whereas PIGF concentration was only negatively correlated with nocturnal hypertension, associated with increased non-dipper type change shown in ABPM." (PMID 38017185, 2024).
breast carcinoma (7 papers, 2015 to 2024). "PIGF and sFlt1 on the other hand have been known to play a major role in preeclampsia, and even associated with a lower breast cancer risk later in life of those patients." (PMID 27464822, 2016). "Some of tumor-derived metabolites such as 5-lipoxygenase in a breast cancer model and placental growth factor (PIGF) in gliomas have been proposed to promote Breg." (PMID 34867973, 2021). "VEGF and PIGF are overexpressed factors in M2-TAMs and breast cancer cells, promoting the progression and metastasis of breast cancer when released in the TME." (PMID 33322132, 2020). "In addition, VEGF and placental growth factor (PIGF), which are overexpressed in M2 TAMs and breast cancer cells, have been shown to work synergistically in mediating tumor progression and immunosuppression." (PMID 34683963, 2021). "Furthermore, a previous study has also shown upregulation of PIGF in breast cancer patients, undergoing combination therapy of anthracyclines and trastuzumab, followed by sensitivity analysis which showed increased risk of developing cardiotoxicity with an increase in the level of PIGF." (PMID 36034829, 2022). "Moreover, a statistical significant correlation was also proven for survived breast cancer patients being either CTC negative or CTC positive in respect to the vascular marker PIGF." (PMID 27464822, 2016). "Within this study we analysed the distribution of angiogenic markers: sFlt1, PIGF, VEGF, VEGF-C and VEGF-D and reveal the differences of their expression in the sera of breast cancer patients with and without circulating tumour cells." (PMID 27464822, 2016).
fetal growth restriction (6 papers, 2017 to 2023). A fetus that does not grow beyond the 10th percentile of conventionally accepted weight for gestational age. "Early-onset PE, defined as onset before 34 weeks, is characterized by defective placental implantation and deficient spiral artery remodeling, leading to intrauterine growth restriction and altered expression of placental proteins (sFtl-1) and growth factors (PIGF)." (PMID 36766955, 2023). "The two comprehensive results exacerbate placental ischemia/hypoxia and alter the release of sFLT-1 and PIGF from the placenta, which lead to the occurrence of maternal hypertension, proteinuria, and fetal growth restriction, i.e., PE." (PMID 36894970, 2023). "This might be physiologically plausible as PIGF levels are associated with other non-placental factors and intrauterine growth restriction; in contrast to sFlt-1 levels which have a strong correlation with the placenta." (PMID 35761268, 2022). "Therefore, PIGF is used to evaluate the maternal condition and intrauterine growth restriction." (PMID 28598396, 2017).
endothelial dysfunction (5 papers, 2021 to 2025). In vascular diseases, endothelial dysfunction is a systemic pathological state of the endothelium (the inner lining of blood vessels) and can be broadly defined as an imbalance between vasodilating and vasoconstricting substances produced by (or acting on) the endothelium. "Endothelial dysfunction caused by PIGF is a common condition in CAA, highlighting the complex relationship between CAA and PIGF in vascular pathology." (PMID 40004604, 2025). "Additionally, cardiac fibroblast‐derived exosomes enriched with miR‐200a‐3p have been associated with endothelial dysfunction, via changes in the VEGF‐A/PIGF signalling cascade, suggesting new mechanisms underlying endothelial dysfunction during cardiac fibrosis." (PMID 35306667, 2023). "These mediators contribute to endothelial dysfunction and systemic inflammation by counteracting pro-angiogenic molecules, such as placental growth factor (PIGF) and VEGF." (PMID 40507775, 2025). "The understanding of the miR-200a-3p/Ets-1/PIGF/VEGF-A axis provides new insights in the endothelial dysfunction mechanisms involved during cardiac fibrosis." (PMID 33969024, 2021). "To investigate whether miR-200a-3p mediates endothelial dysfunction via PIGF, we measured PIGF expression in ECs after treatment with exosomes-derived from scrambled control- or miR-200a-3p antagomir-treated NRVFs with or without TGFβ." (PMID 33969024, 2021).
COVID-19 (4 papers, 2022 to 2023). A disease caused by infection with severe acute respiratory syndrome coronavirus 2. "The presented meta-analysis investigated the influence of COVID-19 on the sFlt-1/PIGF ratio during pregnancy." (PMID 36769707, 2023). "The purpose of this meta-analysis was to examine previously reported findings on the effect of infection and the severity of COVID-19 on the sFlt-1/PIGF ratio during pregnancy." (PMID 36769707, 2023). "This meta-analysis showed the influence of COVID-19 on the sFlt-1/PIGF ratio during pregnancy." (PMID 36769707, 2023). "In this study we found persistent elevation of multiple mediators – IL-6, TNFα, SAA, Tie-2, Flt1, PIGF, and CRP – and persistent depression of IL-7 and bFGF in patients recovering from COVID-19 several months following their acute infection." (PMID 36844209, 2023).
diabetes (4 papers, 2021 to 2023). "Increased serum levels of ANGPTL-4, syndecan-1, PIGF, and IL-8 were observed in diabetes patients with complications." (PMID 34650995, 2021).
colorectal cancer (3 papers, 2014 to 2024). A primary or metastatic malignant neoplasm that affects the colon or rectum. "PIGF/Flt-1 signalling is integral in colorectal cancer progression through increasing the phosphorylation of p38 MAPK, thereby upregulating MMP9 expression; resulting in increasing cellular migration/invasion." (PMID 35154142, 2022). "Our previous studies on the role of ARNO in colorectal cancer tissues have revealed a high correlation with pEGFR and pIGF-IR, suggesting that ARNO possibly enhances the activation and signaling of EGFR and IGF-IR." (PMID 24618737, 2014). "The strong expression of ARNO in colorectal cancer tissue and its significant correlation with pEGFR and pIGF-IR prompted us to wonder whether blocking cytohesins in vivo can inhibit the proliferation of tumor cells." (PMID 24618737, 2014). "Several pro-angiogenic (VEGF, Ang-2, PIGF, sVCAM-1, MCP-1, MMP-3, CHI3L1, IL-8 and CXCL16) and ECM-degrading (MMP-2 and MMP-7) proteins are known to be elevated after colorectal cancer resection, but in relation to postoperative complications such research remain scarce." (PMID 39167197, 2024). "To verify the hypothesis that ARNO is related to colorectal cancer by activating EGF and IGF, we performed immunohistochemistry of resected human colorectal adenocarcinomas stained by ARNO, pEGFR, and pIGF-IR." (PMID 24618737, 2014).
melanoma (3 papers, 2020 to 2022). A malignant, usually aggressive tumor composed of atypical, neoplastic melanocytes. "These experiments with inhibitors of VEGF receptor activities confirm the conclusion from the experiments with PIGF-treated melanomas that VEGF165 stimulated melanoma migration through VEGFR1." (PMID 35997849, 2022). "According to our best knowledge, secretion of PIGF by melanoma-associated fibroblasts has not been reported before." (PMID 35538545, 2022). "Secretion of GM-CSF, DPPIV, ICAM1 and PIGF by melanoma-associated fibroblasts was not reported before." (PMID 35538545, 2022). "Furthermore, fibroblasts activated by melanoma cells showed upregulation of the MMPs’ expression mediators’ levels (pERK, p-p38, CD44, RUNX), enhanced secretion of lactate, several cytokines (IL8, IL6, CXCL1, CCL2, ICAM1), and proteins related to angiogenesis (GM-CSF, DPPIV, VEGFA, PIGF)." (PMID 35538545, 2022).
placental insufficiency (3 papers, 2020 to 2022). Failure of the placenta to deliver an adequate supply of nutrients and oxygen to the fetus. "Serum parameters reflecting placental insufficiency, such as sFlt-1/PIGF, might help detect cases of SGA with a higher risk of APO, but their meaning for APO prediction in high-risk cohorts is still controversial." (PMID 35807137, 2022). "Our study suggests circulating SPINT1 around 36 weeks’ gestation may have a considerably stronger association with several indicators of placental insufficiency than PIGF." (PMID 32415092, 2020). "In contrast, the associations between PIGF and these indicators of placental insufficiency were either not significant, or more modest." (PMID 32415092, 2020).
dementia (2 papers, 2025). Loss of intellectual abilities interfering with an individual's social and occupational functions. "A multisite observational cohort study reported that there is a significant association between PIGF and cognitive impairment associated with white matter injury and dementia." (PMID 40004604, 2025). "Several biomarkers, including ADRD (Alzheimer’s disease and related dementias) biomarkers (Ab, tau, NfL, and GFAP) and angiogenic factors (VEGF, Flt-1, Tie-2, PIGF, and FGF) have been associated with the development of dementia." (PMID 41306424, 2025).
glaucoma (2 papers, 2014 to 2023). Increased pressure in the eyeball due to obstruction of the outflow of aqueous humor. "In a mouse model of glaucoma filtration surgery, the authors reported improved surgical outcome with increasing bleb survival and bleb area following intracameral injection of anti-PIGF." (PMID 26997808, 2014). "They hypothesized that PIGF may be a potential therapeutic target for glaucoma surgery, and proposed that a combination of optimal-dosing anti-PIGF with suboptimal-dosing anti-VEGF may be more effective at reducing scar formation compared to monotherapy with either agent alone." (PMID 26997808, 2014).
heart failure (2 papers, 2019 to 2021). Inability of the heart to pump blood at an adequate rate to meet tissue metabolic requirements. "Studies conducted in patients with heart failure and in patients with PE have found a possible common pathophysiological pathway mediated by angiogenic/anti-angiogenic placental markers like PIGF and sFlt-1." (PMID 34879854, 2021).
intrahepatic cholangiocarcinoma (2 papers, 2021 to 2022). A carcinoma that arises from the intrahepatic bile duct epithelium in any site of the intrahepatic biliary tree. "For example, a subset of quiescent cancer-associated fibroblasts (CAFs) was found to be enriched in the tissue culture of intrahepatic cholangiocarcinoma (ICC) after the blockade of placental growth factor (PIGF)." (PMID 34572523, 2021).
myocardial infarction (2 papers, 2020 to 2022). Gross necrosis of the myocardium, as a result of interruption of the blood supply to the area, as in coronary thrombosis. "It is reported that the administration of PIGF improves cardiac function and decreases inflammatory cytokines in a rat myocardial infarction model, and PDGF-BB has an anti-apoptotic effect on cardiomyocytes." (PMID 32070429, 2020).
Obesity (2 papers, 2021 to 2022). Accumulation of substantial excess body fat. "The main finding of our study is that APO can be predicted by sFlt-1/PIGF, not only in the group of normal and overweight women, but also in women with obesity, considering the decreasing prognostic value." (PMID 35683415, 2022). "There is growing evidence that obesity might influence the level of sFlt-1/PIGF and, therefore, the aim of the study was the evaluation of sFlt-1/PIGF as an APO predictor in obese women with PE." (PMID 35683415, 2022). "In contrast to normal or overweight women, a ratio of sFlt-1/PIGF < 38 could not rule out APO in women with obesity." (PMID 35683415, 2022).
acute myeloid leukemia (1 paper, 2022). Acute myeloid leukemia (AML) is a group of neoplasms arising from precursor cells committed to the myeloid cell-line differentiation. "sFlt-1 is expressed in several tumors, including breast cancer, colorectal cancer, and acute myeloid leukemia (AML), and the PIGF/sFlt-1 ratio, as well as sFlt-1, have been linked to the prognosis of a variety of malignancies." (PMID 35872912, 2022).
asthma (1 paper, 2024). "This is consistent with the study's findings, which observed that higher genetically predicted levels of PIGF (OR = 1.0005; p = 0.0304) increased the risk of asthma in children." (PMID 38730525, 2024). "Glutathione S‐transferase omega‐1 (GSTO1), leukocyte immunoglobulin‐like receptor subfamily B member 4 (LIRB4), and placental growth factor (PIGF) were associated with a greater risk of childhood asthma." (PMID 38730525, 2024).
atherosclerosis (1 paper, 2025). A disease characterized by the build-up of fatty material and calcium deposition in the arterial wall resulting in partial or complete occlusion of the arterial lumen. "Aldosterone-activated MR regulates the expression of target genes, such as placental growth factor (PIGF), promoting the proliferation of VSMCs and the aggregation of monocytes and contributing to the development of atherosclerosis." (PMID 40244230, 2025).
breast tumor (1 paper, 2015). "We addressed the question whether or not the expression levels of ANG-2 and PIGF when considering the overall breast tumor have impact on the survival (considered here as relapse free survival)." (PMID 25768678, 2015).
cerebral microbleeds (1 paper, 2025). Cerebral microbleeds are a group of pathological processes affecting the small arteries, arterioles, capillaries and venules of the brain, as detected by brain imaging techniques. "Others have also found elevated PIGF levels in people with a higher burden of white matter injury and cerebral microbleeds associated with AD." (PMID 40004604, 2025).
cervical dystonia (1 paper, 2024). "The same study also showed an increased population of B cells, monocytes, and an increased ratio of CD8+ cytotoxic cells compared to CD4+ helper cells with an increase in proinflammatory cytokines like IL-5, IL-2, PIGF, VEGF-D, IL-1ß in patients of cervical dystonia." (PMID 39651491, 2024).
childhood asthma (1 paper, 2024). "Elevated levels of seven proteins (TLR4, UBP25, CBR1, Rac GTPase‐activating protein 1 [RGAP1], IL‐21, MICB, and PDE4D) and decreased levels of three proteins (GSTO1, LIRB4 and PIGF) were associated with an increased risk of childhood asthma." (PMID 38730525, 2024). "Future research necessitates larger sample sizes and more comprehensive cellular experiments and animal models to validate the therapeutic efficacy of PIGF protein in the treatment of childhood asthma." (PMID 38730525, 2024). "This suggests that the PIGF protein may serve as a potential therapeutic target for treating childhood asthma." (PMID 38730525, 2024). "Based on the genetic data of 4419 (of 4489) plasma proteins from UK Biobank, our study presents compelling evidence linking 10 plasma proteins (GSTO1, LIRB4, PIGF, IL‐21, MICB, PDE4D, RGAP1, TLR4, UBP25 and CBR1) to childhood asthma." (PMID 38730525, 2024).
Cognitive impairment (1 paper, 2025). Abnormal cognition is characterized by deficits in thinking, reasoning, or remembering. "In addition, PIGF can help distinguish whether cognitive impairment is the result of AD or an issue involving other vascular issues." (PMID 40004604, 2025).
colorectal adenocarcinoma (1 paper, 2014). The most common type of colorectal carcinoma. "Therefore, we used immunohistochemistry to investigate primary human colorectal adenocarcinomas with an antibody detecting ARNO, pEGFR (pY1068), and pIGF-IR (pY1185)." (PMID 24618737, 2014).
coronary heart disease (1 paper, 2023). "In addition, PIGF may also be a short-term prognostic biomarker of coronary heart disease risk." (PMID 37787982, 2023).
fibrosarcoma (1 paper, 2012). A malignant mesenchymal fibroblastic neoplasm affecting the soft tissue and bone. "We demonstrated the feasibility of coculture using HT-1080 fibrosarcomas encapsulated in alginate beads, as these cells are highly angiogenic and secrete a variety of angiogenic factors, including PIGF, a potent angiogenic factor that promotes pathologic angiogenesis." (PMID 23226527, 2012).
glioblastoma (1 paper, 2023). The most malignant astrocytic tumor (WHO grade IV). "Currently, a variety of indicators are used to assess the response to anti-angiogenic therapies in recurrent glioblastoma, including non-invasive diagnostic biomarkers such as phosphatidylinositol-glycan biosynthesis class F (PIGF), interleukin-8 (IL-8) and circulating collagen IV." (PMID 36732815, 2023).
heart defects (1 paper, 2022). "Previous studies have reported that in cases of isolated major fetal heart defects, maternal serum placental growth factor (PIGF) decreases at 11–13 weeks of gestation, which indicates that placental angiogenesis was impaired in the first trimester of pregnancy." (PMID 36233829, 2022).
HELLP syndrome (1 paper, 2020). A life-threatening condition that can potentially complicate pregnancy. "Studies have shown that levels of anti-angiogenic factors (sFlt-1 and sEng) elevated and concentrations of pro-angiogenic mediators (PIGF) decreased in pregnant women with HELLP syndrome." (PMID 33126866, 2020).
hematoma (1 paper, 2023). A hematoma is a collection of blood from a vascular structure into an extravascular space. "PIGF and sVEGFR-1 were also reported to be relatively higher in hematomas than in the sera of the patients with cSDH, which showed PIGF involvement in local inflammation and angiogenesis." (PMID 37958242, 2023).
Hyperglycemia (1 paper, 2023). An increased concentration of glucose in the blood. "Hyperglycemia disturbs trophoblast proliferation and invasion via inhibiting the epithelial-mesenchymal transition, altering the protein expression of related proteases (MMP9, MMP2, and uPA) and angiogenic factors (VEGF, PIGF)." (PMID 37091848, 2023).
lung carcinoma (1 paper, 2022). "For example, increased CXCL1 and PIGF expression promotes the expansion of lung CSCs, which in turn leads to the recurrence of lung cancer." (PMID 36411463, 2022).
lymphoma (1 paper, 2014). A malignant (clonal) proliferation of B- lymphocytes or T- lymphocytes which involves the lymph nodes, bone marrow and/or extranodal sites. "In addition, strong expressions of pSTAT3 and pIGF-IR were detected in most of the lymphoma cells." (PMID 25026277, 2014).
macular edema (1 paper, 2020). "Thus, PIGF and IL-8 could promote chemotaxis and adhesion of leukocytes that reduces the MBR in CRVO patients with macular edema." (PMID 32503534, 2020).
placenta accreta (1 paper, 2022). The clinical condition in which any part of the placenta invades and is inseparable from the uterine wall. "Elevated first-trimester serum placental growth factor (PIGF) was significantly associated with placenta accreta, indicating the potential role of PIGF in identifying high-risk pregnancies for placenta accreta." (PMID 35860796, 2022).
placental abruption (1 paper, 2023). Vaginal bleeding preceding the 20th week of gestation. "Moreover, when compared with patients with PE but without placental abruption, the number of EPCs is reported to be markedly reduced with increased sFlt-1 and decreased PIGF levels in women with PE and placental abruption." (PMID 37986615, 2023).